STAT1 (signal transducer and activator of transcription 1)
Diseases named in the same sentence as STAT1 in open-access papers (continued):
Sharing a sentence is not in itself a finding about the gene and the disease.
measles (6 papers, 2009 to 2025). A highly contagious viral infection caused by the measles virus. "In the cases of RNA viruses, including influenza A, measles, and coronavirus disease, downregulation of genes such as Ddx58, Il1b, Stat1, Stat2, Oas3, Oas2, Oas1a, Oas1g contributes to increased susceptibility to infections." (PMID 40206211, 2025). "Thus, it was determined that protein C suppresses the signaling pathway of INFγ in measles by inhibiting the dimerization of the phosphorylated STAT1 protein, and sites 13, 25, 39, 44, 78, 104, and 168 were found to be related to this activity." (PMID 31892101, 2019). "We found that hPIV3-C interacts directly through its C-terminal domain with STAT1 and GRB2, whereas C proteins from measles or Nipah viruses failed to do so." (PMID 19806178, 2009).
myocardial ischemia (6 papers, 2009 to 2025). A disorder of cardiac function caused by insufficient blood flow to the muscle tissue of the heart. "Cardiomyocyte apoptosis is a major cause of myocardial ischemia/reperfusion (MI/R) injury, in which the activation of the signal transducer and activator of transcription 1 (STAT1) plays an important role." (PMID 31171760, 2019). "It has been shown that myocardial ischemia and reperfusion induced a rapid activation of Stat1." (PMID 20011528, 2009). "It was found that in animal models of myocardial ischemia, DZHSI mainly reduces myocardial cell apoptosis and relieves myocardial ischemia by down-regulating apoptotic factors such as caspase 3 and STAT1." (PMID 34539390, 2021).
osteomyelitis (6 papers, 2021 to 2025). An acute or chronic inflammation of the bone and its structures due to infection with pyogenic bacteria. "We present a pair of Chinese siblings with novel de novo heterozygous missense mutation in exon 23 of the STAT1 gene, which was identified after the index patient presented with multifocal osteomyelitis following Bacillus Calmette–Guerin (BCG) vaccination." (PMID 39840042, 2024). "Besides, osteomyelitis is a common concurrent symptom in MSMD patients with AD STAT1 deficiency, potentially caused by impaired-IFN-γ mediated suppression of osteoblast differentiation and bone resorption." (PMID 40491431, 2025). "Limited data suggest that MSMD with osteomyelitis is a hallmark of STAT1-LOF." (PMID 33777053, 2021). "STAT1 LOF deficiency is a more complicated underlying cause of early-onset MSMD, osteomyelitis, respiratory tract infections, and Herpesviridae infection." (PMID 33777053, 2021). "In a recent systematic review, the clinical spectrum of AD STAT1 deficiency is diverse and most commonly manifests as MSMD, of which Mycobacterium bovis from BCG was the most common pathogen, and multifocal osteomyelitis is also a relatively common reported feature." (PMID 39840042, 2024). "The risk of MSMD in STAT1 LOF patients with osteomyelitis was 6.77 times higher than that in those without osteomyelitis." (PMID 33777053, 2021).
Rotavirus infection (6 papers, 2016 to 2024). Infection with any of the rotaviruses. "In addition, IL-22 producing ILC3 have been implicated in the control of rotavirus infection within the gut epithelium by stimulating STAT1-dependent interferon stimulated gene (ISG) expression in intestinal epithelial cells." (PMID 30893756, 2019). "A cooperation between innate lymphoid cell (ILC)-derived IL-22 and IFN-λ was required for the optimal expression of STAT1 in IECs, leading to enhanced expression of ISGs by these cells and subsequent control of rotavirus infection in vivo." (PMID 30818341, 2019). "For example, interferon-lambda (IFNλ) can mediate a STAT1-dependent protection from rotavirus infection in alliance with IL-22, whereas interferon-alpha (IFNα) and IL-22 may conspire to aggravate graft versus host disease via STAT1." (PMID 33851257, 2021). "Our results indicated that, in HT-29 cells with both microorganisms before rotavirus infection, the relative expression of SOCS3, IFN-γ, STAT1, and IL-10 was significantly (p < 0.05) upregulated." (PMID 38791551, 2024). "We used mouse strains deficient in type-specific IFN signaling, STAT1 and Rag2 to dissect distinct and overlapping contributions of type I and type III IFNs to protection against homologous murine (EW-RV strain) and heterologous (non-murine) simian (RRV strain) rotavirus infections in suckling mice." (PMID 27128797, 2016).
schizophrenia (6 papers, 2018 to 2025). A major psychotic disorder characterized by abnormalities in the perception or expression of reality. "Activation of STAT1 is downstream of cytokine receptors that signal from specific pro-inflammatory cytokines known to be dysregulated in schizophrenia, such as IFNγ, IL-6, IL-2, and IL-10." (PMID 40259965, 2025). "A previous study suggested that activated phosphorylated STAT1 levels may provide a measure of the biological relevance of increased cytokine levels in schizophrenia." (PMID 40259965, 2025). "In conclusion, our findings illustrate an epigenetic mechanism by which upregulation of lncRNA RP5-998N21.4 underlies the development of schizophrenia via the enhancement of IFIT2- and IFIT3-mediated immune defense responses through activation of STAT1 signaling pathways." (PMID 35232977, 2022).
serous ovarian cancer (6 papers, 2017 to 2026). "To elucidate STAT1’s mechanistic role in OV prognosis, we identified the top 100 co-expressed genes (Pearson’s |r| >0.55) showing strongest associations with STAT1 expression in TCGA high-grade serous ovarian carcinoma cohorts." (PMID 40849492, 2025). "High-level STAT1 associated with a better outcome of survival in patients with high-grade serous ovarian cancer." (PMID 33834023, 2021). "In high-grade serous ovarian cancer (HGSC), higher STAT1 expression correlated with increased progression-free survival and predicted better prognosis." (PMID 28536310, 2017).
skin cancer (6 papers, 2013 to 2025). "Recent findings have revealed its involvement in collective invasion, notably in skin cancer cells with high metastatic potential, where the interferon‐β/STAT1 axis serves as the driving force." (PMID 40674249, 2025). "Consistently, we observed inflammatory genes, including Ifng, Stat1, Ifit2, Ifit3, Isg15, and Bst2, being highly expressed in the T cell cluster in skin tumors." (PMID 40282557, 2025). "Consistent with this, treatment of RHE with THDC alone (but not THDC + AZ) led to up-regulation of genes belonging to the “unhealthy skin signature” as well as the STAT1-57 gene module, which is also activated under pathological conditions such as wounding and skin cancers." (PMID 34445461, 2021).
systemic sclerosis (6 papers, 2021 to 2023). A chronic disorder, possibly autoimmune, marked by excessive production of collagen which results in hardening and thickening of body tissues. "In a recent work on patients with RA (n = 29) and Systemic Sclerosis (n = 21), the former showed a higher baseline level of STAT1 and STAT3 phosphorylation in CD3+ T cells and monocytes compared with healthy controls." (PMID 35958600, 2022). "Among the eight TFs selected STAT1 and STAT2 have been previously demonstrated to be constitutively upregulated in monocytes from Systemic Sclerosis patients and to correlate with the expression of STAT-target genes." (PMID 36406275, 2022).
uveitis (6 papers, 2021 to 2025). An inflammatory process affecting a part of or the entire uvea. "On the other hand, increase of IFN-γ-producing Th1 cells in the eye and LN of the CD4-IRF4KO mice is also consistent with reports that IFN-γ contributes to the suppression of Th17 cells that mediate uveitis through activation of IL-27/STAT1 pathway." (PMID 33803441, 2021). "The Th1 and Th17 cell subsets require STAT1 and STAT3 during development and may be the etiological agents responsible for human uveitis and scleritis and experimental autoimmune uveoretinitis." (PMID 34966823, 2021). "As induced rodent models of uveitis have shown that either Th1 or Th17 T lymphocytes can promote experimental uveitis, the ability of SOCS1-KIR to regulate both STAT1 and STAT3 signaling may be particularly valuable in inhibiting uveitogenic effector functions." (PMID 35505065, 2022).
alopecia areata (5 papers, 2018 to 2025). Loss of scalp and body hair involving microscopically inflammatory patchy areas. "IFNγ-mediated STAT1 activation is also implicated in the pathogenesis of hidradenitis suppurativa and alopecia areata." (PMID 39161766, 2024). "In HaCat and Jurkat cells, as well as in peripheral blood mononuclear cells (PBMCs) from alopecia areata patients, a concentration of 40 μM EGCG effectively suppressed STAT1 phosphorylation (p-STAT1)." (PMID 39765834, 2024).
Anxiety (5 papers, 2022 to 2025). Intense feelings of nervousness, tension, or panic often arise in response to interpersonal stresses. "The overexpression of AU020206 in the prefrontal cortex increases the expression levels of STAT1 and cytokines and causes anxiety behaviors in the female mice." (PMID 39310110, 2024).
ataxia telangiectasia (5 papers, 2022 to 2025). Ataxia-telangiectasia is the association of severe combined immunodeficiency (affecting mainly the humoral immune response) with progressive cerebellar ataxia. "SCID, CIDs, DiGeorge syndrome, Wiskott-Aldrich syndrome, Ataxia telangiectasia, Dyskeratosis congenita, ORAI-1 deficiency, CGD, X-linked Agammaglobulinemia, ALPS, STAT1 gain of function, CTLA-4 deficiency, GATA-2 deficiency, TRAPS, FMF, NEMO, TIM3, DOCK8, STAT2, STAT3, PIK3CD." (PMID 41049857, 2025).
autoimmune hepatitis (5 papers, 2020 to 2025). Hepatitis caused by autoantibodies. "BBR activated the AMPK pathway on concanavalin-A-induced autoimmune hepatitis (AIH) in mice and affected the JAK/STAT signaling pathway by the reduction in STAT1 and STAT4 phosphorylation, leading to suppressed Th1 differentiation and function in different animal models." (PMID 35631330, 2022). "In particular, STAT1 GOF and CVID patients with dysregulation exhibited low frequencies of cTfh17 but increased frequencies of cTfh1 cells, reduced frequencies of Sw-MBL and hypogammaglobulinemia (with the exception of P1 that coursed with autoimmune hepatitis and hypergammaglobulinemia)." (PMID 33193371, 2020).
biliary atresia (5 papers, 2013 to 2024). A rare, biliary tract disease characterized by progressive obliterative cholangiopathy of the intra- and extrahepatic bile ducts, occurring in the embryonic/ perinatal period, leading to severe and persistent neonatal jaundice and acholic stool. "For example, SPP1, TGFB1, JAG1, STAT1, and VIM were linked to congenital biliary atresia, and were confirmed to be strongly expressed in the endothelial and megakaryocyte." (PMID 34095116, 2021). "Inborn errors of immunity such as STAT1 and STAT2 in human infants will also be of interest to examine in the context of biliary atresia development." (PMID 39348381, 2024). "This notion was further strengthened by the fact that Stat1, NF‐κB1, and NF‐κB2 expression correlated with PRC levels in infants with inflammatory signature of biliary atresia." (PMID 32821877, 2020).
chronic kidney disease (5 papers, 2015 to 2024). Impairment of the renal function secondary to chronic kidney damage persisting for three or more months. "Activation of the JAK/STAT-1 pathway can upregulate IL-1 and transforming growth factor-b (TGF-b) expression in the kidney, making STAT-1 a potential therapeutic target for chronic kidney disease." (PMID 39376880, 2024). "The protein levels of COX-2, iNOS and p-STAT1 in the kidney tissues of rats with chronic renal failure induced by adenine were examined by Western Blotting." (PMID 29643988, 2018). "Further study indicated that KJY inhibited STAT1 activation by down regulating p-STAT1 to exert anti-inflammatory effect and improve renal function in rats with chronic renal failure." (PMID 29643988, 2018). "Moreover, our study indicated that KJY exerted considerable therapeutic effects on inhibiting STAT1 activation to reduced the secretion of inflammatory cytokines and improve the renal function of rats with adenine-induced chronic renal failure." (PMID 29643988, 2018). "We used data from a large genome-wide association study to examine whether common SNPs in any of the genes encoding the kidney aging transcription factors (STAT1, STAT3 and the canonical NFκB complex genes RELA and NFKB1) show an association with kidney function or chronic kidney disease." (PMID 26678048, 2015).
colon adenocarcinoma (5 papers, 2022 to 2023). "Using The Cancer Genome Atlas (TCGA) database, we found a positive correlation between colorectal CSC-associated markers and STAT1 expression in patients with colon adenocarcinoma." (PMID 35313878, 2022). "To determine the relevance of our findings in human Colon adenocarcinoma, we assessed IFNγ/STAT1/IRF7/IFI35/CD8 expression with Timer database." (PMID 37380972, 2023). "Using the TCGA database, we found positive correlations between the expression of angiogenesis-related markers and STAT1 in patients with colon adenocarcinoma." (PMID 35313878, 2022). "The expression of STAT1 was increased in human colon adenocarcinoma cells compared to normal human colon epithelial cells." (PMID 35313878, 2022). "Colon adenocarcinoma with dysplasia was observed in the mouse model of AOM/DSS-induced CRC, and the expression of STAT1 in colorectal tumor tissues was evaluated by IHC staining." (PMID 35313878, 2022).
colorectal tumor (5 papers, 2018 to 2025). "has shown that inhibition of TRIB3 signalling increases CD8+ T cell accumulation in colorectal tumours in a similar STAT3/STAT1/CXCL10 dependent mechanism." (PMID 39165364, 2024). "However, the expression of IFIT2 induced by the IFN-γ/JAK/STAT1 signaling was significantly higher in colorectal tumor cells compared to IFNα induction." (PMID 40909948, 2025). "In the GSE32323 datasets, RNA sample data from paired colorectal tumors and control tissues of 17 CRC patients were extracted, and the expression of STAT1 was found to be higher in adenomas than in normal tissues." (PMID 35313878, 2022). "Furthermore, PHF8 mRNA levels negatively correlated with IFNG, TLR3, IFIH1, STAT1 and OASL expression, suggesting that PHF8 restrains adaptive immune responses in human colorectal tumors." (PMID 37454216, 2023). "In colorectal tumor cells with MET expansion, the upregulation of PD-L1 expression aligns with the activation of the IFN-γ/STAT1 pathway, attributed to the increased phosphorylation of JAK1/2, facilitating STAT1 activation in response to IFN-γ stimulation and promoting the transcription of PD-L1." (PMID 40909948, 2025). "A distribution analysis of nuclear versus cytoplasmic STAT1 in cancer cells of these tissue microarrays revealed that most colorectal tumors were negative for STAT1 in both compartments or positive for STAT1 in the nucleus with or without cytoplasmic STAT1 expression." (PMID 29419930, 2018).
encephalitis (5 papers, 2006 to 2025). An acute inflammatory process affecting the brain parenchyma. "In one case study, an infant with a homozygous mutation in the STAT1 gene succumbed to HSV-1 infection with uncontrolled encephalitis." (PMID 33430330, 2021). "Mice with an N-terminal deletion in Stat1 (129Stat1−/− (N-term)) had transient infection of the liver and spleen, but succumbed to encephalitis by day 10 post-infection." (PMID 21915277, 2011).
gastritis (5 papers, 2014 to 2025). Inflammation of the stomach. "STAT1 was found to be activated in epithelial cells especially in H. pylori positive gastritis and was significantly upregulated in both diffuse type and intestinal type GC." (PMID 35456965, 2022). "We observed that STAT1 was activated in human H. pylori-positive gastritis, while in GC, STAT1, and its target gene, PD-L1, were significantly elevated." (PMID 35456965, 2022). "Other group also revealed that IL-21 regulates Th1 and Th17 effector responses during chronic H. pylori infection in a STAT1- and STAT3-dependent manner, therefore playing a major role controlling H. pylori infection and gastritis." (PMID 25349535, 2014). "In this cohort, we observed that STAT1 expression was significantly upregulated in H. pylori-positive gastritis compared to H. pylori-negative gastritis." (PMID 35456965, 2022). "Treatment with p38 inhibitor induced STAT1 and NF-κB activation in the stomach, as seen in ASK1−/− or ASK1−/−→WT mice, suggesting that ASK1-p38 pathway in myeloid cells is a critical regulator of H. pylori-induced gastritis and metaplasia." (PMID 33542169, 2020).
hepatitis B (5 papers, 2019 to 2025). "Helicobacter hepaticus generate a detrimental immune microenvironment by IFN-γ/p-STAT1 axis which can promote the tumorigenesis of hepatitis B via recruiting innate lymphoid cells." (PMID 31123503, 2019). "ILCs-derived IFN-γ can promote the tumorigenesis of hepatitis B via E-cadherin/STAT1." (PMID 31123503, 2019).
infertile (5 papers, 2020 to 2024). "Heat stress affects the estrous cycle by affecting the ovarian JAK/STAT1 signaling pathway, which in turn leads to infertility in pigs." (PMID 38200837, 2023). "The results showed that the expression levels of MKRN2 and STAT1 were both significantly downregulated in the infertile patients." (PMID 36967804, 2023). "In infertile patients, inflammatory cytokines led to recruitment of NF-κB and STAT1 proteins to the OPN and CD44 promoters, resulting in their overexpression." (PMID 33047155, 2020). "To verify the role of MKRN2 in the male teratozoospermia, we analyzed the expression levels of MKRN2 and STAT1 in 13 normally fertile male patients and eight infertile individuals with a severe and consistent heterogeneous teratozoospermia based on the GEO dataset GSE6872." (PMID 36967804, 2023). "The activation of IL‐6/JAK2/STAT1 and STAT3 signaling pathways are found in the hydrosalpinx in infertile patients, indicating that they might be involved in the pathogenesis of hydrosalpinx." (PMID 37382258, 2023).
intestinal tumors (5 papers, 2012 to 2022). "Loss of these cells in Stat1-deficient intestinal tumors of ApcMin mice resulted in reduced tumor load and increased infiltration of anti-tumor immune cells." (PMID 32444775, 2020). "In summary, we identified Stat1-dependent IDO1+ Paneth cells in intestinal tumors and normal intestinal crypts." (PMID 32444775, 2020). "Moreover, a dual function of STAT1 signaling is also highly discussed during intestinal tumor formation including cell death regulation and immune cell modulation." (PMID 34497340, 2022). "Specifically, Socs1−/− mice spontaneously develop intestinal tumours in an IFNγ/STAT1-dependent manner, suggesting that SOCS1 controls the chronic inflammatory JAK/STAT1 signalling needed for CRC development." (PMID 31091767, 2019).
lung disease (5 papers, 2010 to 2024). "STAT-1/STAT-6 double knockout mice, which reversed the upregulation of M2 macrophages observed in STAT-1-deficient mice, had reduced lung disease and prefibrotic lesions." (PMID 25250029, 2014). "Moreover, deficiency of STAT1 demonstrated a markedly worsening pulmonary disease with inflammation of small airways and alveoli." (PMID 34603282, 2021). "In stark contrast, we demonstrate the paradoxical finding that SARS-CoV Urbani and rMA15 viruses induce severe end stage lung disease by a STAT1 dependent mechanism that is independent of IFN receptor type I, II and III signaling." (PMID 20386712, 2010).